PHF6 (PHD finger protein 6)
Diseases named in the same sentence as PHF6 in open-access papers (continued):
Sharing a sentence is not in itself a finding about the gene and the disease.
leukemia (continued). "Moreover, PHF6 KO B-ALL cells induced a malignancy closer in presentation to lymphoma than leukemia, with tumor cells showing reduced expression of CD19 and B220 and B-cell development genes (e.g., Cd74, IL4ra, Lyn, Ly86, and BLK), and upregulation of CD4 and T-cell signal transduction genes." (PMID 34381727, 2021). "We report here that Phf6 knockout increases the aggressiveness of Hoxa9-driven AML over serial transplantation, and increases the frequency of leukemia initiating cells." (PMID 39004675, 2024). "The percentage of GFP+ leukemia cells was significantly decreased in BM of VC Phf6,MA9 when compared with that of WT Phf6,MA9 mice." (PMID 37393343, 2023). "The percentage of GFP+ leukemia cells and the degree of extramedullary infiltration in spleen, liver, lung, and brain, were increased in VC Phf6 + JAK3M511I mice than Phf6 WT + JAK3M511I mice." (PMID 34465864, 2022). "Although GFP+ leukemia cells in the two groups were mainly CD3+ or CD8+, the percentages of myeloid and B cells were significantly increased in the PB of VC Phf6 + JAK3M511I mice when compared with Phf6 WT + JAK3M511I mice." (PMID 34465864, 2022). "For example, inactivation of PHF6 in hematopoietic progenitors has been reported to facilitate NOTCH1-induced T-ALL, potentially through increasing leukemia-initiating cells and development of a “leukemia stem cell transcriptional program” in lymphoblasts." (PMID 34381727, 2021). "Given that 70% of human AMLs show high HOXA9 levels, we deemed the Hoxa9 overexpression mouse model as being broadly relevant to human leukemia biology, as opposed to MLL-AF9, which does not co-occur with PHF6 mutation in humans." (PMID 39004675, 2024). "In addition, the weight and GFP+ leukemia cells of spleen were reduced in VC Phf6,MA9 mice than that of WT Phf6,MA9 mice." (PMID 37393343, 2023). "Notably, the VC Phf6,RE9a mice showed much milder disease symptoms than WT Phf6,RE9a mice, including lower counts of GFP+ leukemia cells in the PB and BM, higher body weights and lower spleen and liver weights." (PMID 37393343, 2023). "These involve genes which are known to be leukemia drivers (such as FAT1, NOTCH1, PHF6, FLT3), and can activate signaling pathways that push the cells to multiply faster, as well as genes involved in ribosome biogenesis or translational control (such as WDR36 and LTV1)." (PMID 36482893, 2022). "Furthermore, combination therapy with a JAK3 inhibitor (tofacitinib) and a MDM2 inhibitor (idasanutlin) reduces the Phf6 KO and JAK3M511I leukemia burden in vivo." (PMID 34465864, 2022). "However, when we depleted Phf6 in MC Phf6 + JAK3M511I mice with pIpC, leukemia cells were mainly lymphoid cells." (PMID 34465864, 2022). "Further supporting its leukemia-initiating tumor suppressor role, inactivating Phf6 in hematopoietic progenitors, favors the development of NOTCH1-induced T-ALL." (PMID 34440292, 2021). "Furthermore, Phf6 deletion led to more GFP+ leukemia cells apoptosis in the spleen but not in BM of VC Phf6,MA9." (PMID 37393343, 2023).
Börjeson-Forssman-Lehmann syndrome (19 papers, 2015 to 2026). "The plant homeodomain zinc-finger protein, PHF6, is a transcriptional regulator, and PHF6 germline mutations cause the X-linked intellectual disability (XLID) Börjeson-Forssman-Lehmann syndrome (BFLS)." (PMID 38429579, 2024). "PHD finger protein 6 (PHF6) is encoded by a gene mutated in Börjeson–Forssman–Lehmann syndrome and many leukemic cancers." (PMID 37834403, 2023). "Most well-described are mutations in the X-linked gene encoding the PHD-Like Zinc Finger Protein 6 (PHF6) that associates with PAF1c and causes the ID disorder Börjeson–Forssman–Lehmann syndrome (BFLS; OMIM 301900)." (PMID 35615272, 2022). "PHF6 (Plant Homeodomain (PHD)-like Finger protein 6) mutations are associated with Börjeson–Forssman–Lehmann syndrome with some documented cases characterised by behavioural disturbance related to anxiety, compulsive behaviour, and emotional attachment." (PMID 30842574, 2021). "Whole or partial deletion of the PHF6 gene (MIM: 300414) leads to an X-linked disorder called Borjeson-Forssman-Lehmann syndrome (BFLS, MIM: 301900), which usually affects males, but mild to severe symptoms are also present in female carriers." (PMID 34976017, 2021). "The PHD finger protein, homeodomain finger protein 6 (PHF6), is a highly conserved, 365 amino acid, 41kDa protein, that was first identified in the X-linked neurodevelopmental disorder, Börjeson-Forssman-Lehmann syndrome (BFLS)." (PMID 34381727, 2021). "Mutations in PHF6 are associated with Borjeson-Forssman-Lehmann syndrome and are also implicated in the development of cancer, supporting the notion that deregulation of rDNA transcription and rDNA R-loop resolution can result in disease." (PMID 30556094, 2019). "In human disease, R-loop-mediated rDNA damage has been linked to Borjeson-Forssman-Lehmann syndrome (PHF6), Friedreich ataxia (FXN), amyotrophic lateral sclerosis type 4 (SETX), and Fragile X syndrome (FMR1), among others." (PMID 30556094, 2019). "For example, two affected male siblings were found to be hemizygous for a nonsense mutation in PHF6 (Börjeson-Forssman-Lehmann syndrome MIM:301900) inherited from their unaffected mother." (PMID 28554332, 2017). "We show that Phf6, a gene mutated in the cognitive disorder Börjeson-Forssman-Lehmann syndrome, is an important regulatory target for miR-128." (PMID 25556700, 2015). "Borjeson-Forssman-Lehmann syndrome (BFLS) is a rare X-linked disease caused by PHF6 mutations." (PMID 30630810, 2019). "PHF-6 is a gene found in association with the Börjeson-Forssman-Lehmann syndrome." (PMID 31565104, 2019). "Börjeson-Forssman-Lehmann syndrome (BFLS) is an X-linked intellectual disability and endocrine disorder caused by pathogenic variants of plant homeodomain finger gene 6 (PHF6)." (PMID 39405291, 2024). "Among these is the PHD finger protein 6 (PHF6), a gene mutated in Börjeson–Forssman–Lehmann syndrome and leukemic cancers." (PMID 31782600, 2020). "Germline mutations in Phf6 causes the X-linked intellectual disability (XLID), Börjeson-Forssman-Lehmann syndrome (BFLS), characterized by impairments in cognitive function, epileptic-like seizures, and behavioural disturbances, in addition to endocrine defects." (PMID 38429579, 2024).
acute myeloid leukemia (13 papers, 2014 to 2026). Acute myeloid leukemia (AML) is a group of neoplasms arising from precursor cells committed to the myeloid cell-line differentiation. "Mutation of plant homeodomain finger protein 6 (PHF6) occurs in approximately 3% of acute myeloid leukaemia (AML) cases." (PMID 36176187, 2023). "PHF6 serves as a tumor suppressor protein, with PHF6 mutations and deletions often implicated in the development of T-lymphoblastic leukemia and less frequently in acute myeloid leukemia and other myeloid neoplasms." (PMID 34381727, 2021). "Interestingly, PHF6 mutations occur to a lesser extent, in 3% of acute myeloid leukemia, and 3% of high-grade B-cell lymphoma." (PMID 37393343, 2023). "Additionally, PHF6 mutations are present in up to 30% of T-cell acute lymphoblastic leukemia (T-ALL) cases, 3% of acute myeloid leukemia (AML) cases, and some other forms of acute leukemia." (PMID 41515604, 2025). "The first and most well-documented hematologic malignancy harboring mutations of PHF6 is T-lymphoblastic leukemia (T-ALL), with fewer cases identified in acute myeloid leukemia (AML), and rarer cases identified in pre-malignant clonal hematopoiesis." (PMID 34381727, 2021). "Additionally, PHF6 maintains acute myeloid leukemia (AML) through regulation of the NF-κB signaling pathway." (PMID 38813086, 2024). "Indeed, germline mutations in PHF6 are the cause of the Börjeson–Forssman–Lehmann X-linked intellectual disability syndrome (BFLS), while somatic PHF6 mutations have been identified in T-cell acute lymphoblastic leukemia (T-ALL) and acute myeloid leukemia (AML)." (PMID 26103525, 2015).
acute lymphoblastic leukemia (11 papers, 2014 to 2026). Leukemia with an acute onset, characterized by the presence of lymphoblasts in the bone marrow and the peripheral blood. "Mutations in PHF6 also have been reported in the blastic phase CML while p.R274Q variant is a novel mutation in CML which only reported in Early T-cell precursor (ETP) acute lymphoblastic leukemia (COSM306061)." (PMID 35896598, 2022). "Somatic loss-of-function mutations of PHF6 are most commonly seen in T-cell acute lymphoblastic leukemia (T-ALL) (15% of pediatric cases, 35% of adult cases) and wild-type PHF6 is a known tumor suppressor in T-ALL." (PMID 38812997, 2023). "In our study, high transcriptional expression of PHF6 was significantly related to high probability of survival in BLCA which were consistent with the research results in acute lymphoblastic leukemia." (PMID 35503998, 2022). "The high expression of PHF6 can play a role of tumor suppressor in patients with acute lymphoblastic leukemia and as a favorable prognostic factor." (PMID 35503998, 2022). "Loss-of-function mutations in PHF6, encoding a presumed epigenetic regulator, have been primarily described in T cell acute lymphoblastic leukemia (T-ALL) and the first insights into its function in normal hematopoiesis only recently emerged from mouse modeling experiments." (PMID 33251223, 2020). "PHF6 mutations, often found alongside JAK3 mutations in T-cell acute lymphoblastic leukemia (T-ALL) patients, play a critical role in cancer progression by modulating signaling pathways." (PMID 38813086, 2024). "PHF6 mutations are seven times more common in males with AML than in females, whereas PHF6 alterations exclusively occur in males with T-cell acute lymphoblastic leukemia (T-ALL)." (PMID 41562928, 2026). "Interestingly, shRNA-mediated knockdown of Phf6 in a murine B-cell acute lymphoblastic leukemia (B-ALL) model was observed to significantly reduce the rates of tumour proliferation, in contrast to both T-ALL and AML models, where the loss of Phf6 correlates with enhanced tumour progression." (PMID 26103525, 2015). "It is very important to analyze the maintenance role of PHF6 in AML, which is different from its tumor-suppressing function in T-cell acute lymphoblastic leukemia (T-ALL)." (PMID 38336746, 2024).
T-cell acute lymphoblastic leukemia (10 papers, 2014 to 2026). Acute lymphoblastic leukemia of T-cell origin. "In particular, we find enrichment of (CA)n repeats in PHF6 peak summits, consistent with a previous study in T-cell acute lymphoblastic leukaemia (T-ALL) where PHF6 was also shown to bind (CA)n repeats." (PMID 38429579, 2024). "The plant homeodomain finger 6 gene (PHF6) is a tumor suppressor gene known to be involved in T-cell acute lymphoblastic leukemia (T-ALL) (20%) but that has also been noted in about 3% of adult AML in one study." (PMID 39200232, 2024).
Intellectual disability (9 papers, 2013 to 2026). "Mutations that disrupt PHF6 can cause intellectual disabilities, and one possible reason for this is that PHF6 is needed to ensure that the neurons migrate to the correction location." (PMID 25556700, 2015). "Female carriers within BFLS families typically display mild, if any, symptoms, with at least one isolated female patient expressing a de novo PHF6 mutation having been diagnosed with BFLS marked by mild intellectual disability." (PMID 26103525, 2015). "Interestingly, several recent studies describe female patients expressing de novo PHF6 mutations that exhibit more severe intellectual disability than female BFLS carriers, overlapping more closely with Coffin–Siris syndrome than with features of classical BFLS." (PMID 26103525, 2015). "Since the cerebral cortex, an important site of mammalian cognitive function, is often affected in intellectual disability, we focused our attention on defining the role of PHF6 in the cerebral cortex." (PMID 39405291, 2024). "Among them, LAMP2, GRIA3, PHF6, and HPRT1 genes are associated with Danon disease, Intellectual deficiency, X-linked syndrome, Wu type, BFL syndrome, Lesch Nyhan syndrome and other syndromes." (PMID 38031145, 2023). "To test our model of functional antagonism between miR-128 and ARPP21 in development we chose the intellectual disability gene Phf6 as a highly ranked ARPP21 target in the iCLIP experiment." (PMID 29581509, 2018). "Importantly, mutations in PHF6 cause Börjeson-Forssman-Lehmann syndrome (BFLS), characterized by moderate-to-severe intellectual disability and seizures." (PMID 28041881, 2017).
myeloid neoplasm (8 papers, 2021 to 2026). Proliferation of myeloid cells originating from a primitive stem cell. "Here, the authors perform genetic analyses of PHF6-mutant myeloid neoplasms which show specific sex-associated genetic correlations and functional collaboration between PHF6 and RUNX1 associated with prognostic value." (PMID 38418452, 2024). "In summary, concurrent mutations in the SF3B1 and PHF6 genes are rare in myeloid neoplasms, but they do exist." (PMID 36671709, 2022). "As myeloid neoplasms with PHF6 mutations are rare, the clinical characteristics of patients with these myeloid neoplasms are much less established compared to those of patients with myeloid neoplasms with SF3B1 mutations." (PMID 36671709, 2022). "Since SF3B1 and PHF6 mutations can both serve as driver mutations and play key roles in the development of a variety of myeloid neoplasms, it is of clinical importance to clarify the issue of their potential mutual exclusivity." (PMID 36671709, 2022). "In summary, concurrent mutations in SF3B1 and PHF6 are rare, but they do exist in a variety of myeloid neoplasms, with roles as early initiating events and in disease progression, respectively." (PMID 36671709, 2022). "Somatic PHF6 mutations occur more frequently in T-lymphoblastic leukemia/lymphoma and have only been reported in approximately 3% of myeloid neoplasms, which is consistent with our findings in this study." (PMID 36671709, 2022). "We summarize that concurrent mutations in SF3B1 and PHF6 are rare, but they do exist in a variety of myeloid neoplasms." (PMID 36671709, 2022). "The potential role of PHF6 mutations in the pathogenesis of myeloid neoplasms is poorly understood, but PHF6 appears to act as a tumor suppressor gene, regulating the transcription of signaling genes and the DNA damage response." (PMID 36671709, 2022). "All of these data suggest that PHF6 mutations in myeloid neoplasms often arise late as a result of clonal evolution and that increasing levels of PHF6 mutations are associated with poor clinical outcomes." (PMID 36671709, 2022). "Since SF3B1 and PHF6 mutations can both serve as drivers of mutations and play key roles in the development of myeloid neoplasms, it is of clinical importance to clarify this issue." (PMID 36671709, 2022). "Further work is therefore required to determine the mechanism by which PHF6 pushes these neoplasms to a more aggressive disease, as well as to determine the overall prognostic significance of PHF6 mutations in myeloid malignancies in general." (PMID 34381727, 2021). "With regard to disease burden, the percentage of blasts in the bone marrow tended to be higher in patients with myeloid neoplasms harboring PHF6 mutations." (PMID 34381727, 2021). "The largest study of PHF6 mutations in myeloid malignancies involved targeted sequencing of 1760 cases with myeloid neoplasms." (PMID 34381727, 2021). "PHF6 mutations (PHF6MT) are identified in various myeloid neoplasms (MN)." (PMID 38418452, 2024). "It is possible that myeloid neoplasms with SF3B1 and PHF6 double mutations may represent a unique entity among myeloid neoplasms." (PMID 36671709, 2022). "Moreover, PHF6 mutations tend to occur late in the course of myeloid neoplasms, either concurrently with or subsequently to SF3B1 mutations in all cases, and are associated with disease progression in a subset of the cases." (PMID 36671709, 2022). "In this study, we analyzed the NGS panel test results of 6478 patients to address the question of whether SF3B1 and PHF6 mutations are mutually exclusive in myeloid neoplasms." (PMID 36671709, 2022). "It has been reported that PHF6 and NOTCH1 mutations were often implicated in the development of T-ALL and less frequently in AML and other myeloid neoplasms." (PMID 41341582, 2025). "We report the clinicopathologic and molecular features of 21 myeloid neoplasms with double SF3B1 and PHF6 mutations." (PMID 36671709, 2022).
myeloid neoplasm (continued). "Nevertheless, the findings in this study show that myeloid neoplasms with SF3B1 and PHF6 mutations do occur uncommonly, and seem to be associated with some distinctive features." (PMID 36671709, 2022). "The aim of this study is to report a series of myeloid neoplasms in which concurrent SF3B1 and PHF6 mutations were detected, along with their clinicopathologic and molecular features." (PMID 36671709, 2022). "Other co-mutations often seen in myeloid neoplasms with germline RUNX1 are in DNMT3A, FLT3, GATA2, PHF6 (PHD finger protein 6), BCOR (BCL6 Corepressor), WT1, and TET2." (PMID 35054439, 2021). "Further evidence for PHF6 mutations acquired secondarily and leading to progression of myeloid neoplasms was found in patients with germline mutations of RUNX1, where PHF6 mutations were implicated in the transition to MDS in one patient and the transition to AML in the other." (PMID 34381727, 2021). "One possible explanation for myeloid neoplasms with both SF3B1 and PHF6 mutations not having been reported in the literature may be the lack of large-scale studies of myeloid neoplasms that have been assessed for PHF6 mutations." (PMID 36671709, 2022).
myelodysplastic syndrome (5 papers, 2021 to 2024). A clonal hematopoietic disorder characterized by dysplasia and ineffective hematopoiesis in one or more of the hematopoietic cell lines. "With respect to mixed myelodysplastic syndrome/myeloproliferative neoplasm cases, PHF6 mutations were seen in 4.7% of CMML patients." (PMID 34381727, 2021). "Animal models suggest a possible role for PHF6 mutations in myelodysplastic syndrome (MDS), as aged mice with knocked-out PHF6 exhibit megakaryocytic dysplasia and associated decreased platelet counts as well as extramedullary hematopoiesis." (PMID 34381727, 2021). "Myeloid gene mutations: RUNX1 44.14%, U2AF1 40.74%, PHF6 (c.663_668clclims13) 6.3%, PHF6 (c.725G>A) 73.26%; myelodysplastic syndrome (MDS)-FISH were all negative." (PMID 38457569, 2024). "Somatic PHF6 mutations are seen in 38% of T-cell acute lymphocytic leukemia (T-ALL), in 3–6% of AML, myelodysplastic syndrome (MDS), and chronic myelomonocytic leukemia (CMML), and in 23% of mixed-phenotype acute leukemia (MPAL) and undifferentiated leukemia." (PMID 39004675, 2024).